PTPN22 (protein tyrosine phosphatase non-receptor type 22)
Diseases named in the same sentence as PTPN22 in open-access papers (continued):
Sharing a sentence is not in itself a finding about the gene and the disease.
renal carcinoma (1 paper, 2026). A carcinoma arising from the epithelium of the renal parenchyma or the renal pelvis. "To further assess the functional consequences of PD-L1 downregulation mediated by PTPN22 knockdown, we co-cultured renal cancer cells with Jurkat cells stably expressing both PD-1 and a NFAT luciferase reporter." (PMID 41522360, 2026). "Renal cancer cells with PTPN22 knockdown exhibited reduced green fluorescence, indicating that PTPN22 silencing diminishes the capacity of cancer cells to bind PD-1 by lowering PD-L1 levels; this effect was reversed by PD-L1 overexpression." (PMID 41522360, 2026). "This suggests that curcumin effectively downregulates PTPN22/p-CBL Y700/PD-L1 and promotes T cell activation, thereby enhancing the tumor immune microenvironment and inhibiting renal cancer growth." (PMID 41522360, 2026). "The results demonstrated that knockdown of PTPN22 did not directly impact the proliferation or growth of renal cancer cell lines either in vitro or in vivo." (PMID 41522360, 2026).
thoracic aortic aneurysm/dissection (1 paper, 2022). "Moreover, transcriptomics data revealed that PTPN22 is a potential biomarker for AAA with limited diagnostic value in patients with thoracic aortic aneurysm/dissection." (PMID 36588574, 2022).
thyroid cancer (1 paper, 2021). "Our research group used bioinformatics to analyze the Oncomine database and found that HT-related genes (TSHR, BACH2, RNASET2, CTLA4, PTPN22, IL2RA) were expressed in different types of thyroid cancer." (PMID 34993154, 2021). "Among them, TSHR and RNASET2 were highly expressed in malignant tumors, especially TSHR in thyroid cancer, while BACH2, CTLA4, PTPN22, IL2RA, and other immune-related genes are expressed significantly lower in thyroid cancer." (PMID 34993154, 2021).
urticaria (1 paper, 2025). A vascular reaction of the skin characterized by erythema and wheal formation due to localized increase of vascular permeability. "Among other genes, Protein tyrosine phosphatase‐22 (PTPN22) has been studied by several authors in relation to urticaria." (PMID 40635160, 2025).
vitamin deficiency (1 paper, 2016). A disorder that is caused by the deficiency of a vitamin. "We next analysed, whether PTPN22 variation might be associated with malabsorption and vitamin deficiency in IBD patients." (PMID 27467733, 2016).
tumor (107 papers, 2010 to 2026). "The enhanced anti-tumour function of PTPN22-deficient CD8+ T cells was particularly evident in response to tumours expressing low-affinity TCR antigens and was associated with elevated cytokine secretion and direct TCR-dependent cytotoxicity." (PMID 38334623, 2024). "L-1 treatment in WT mice phenocopies PTPN22-deficiency in terms of enhancing T cell and myeloid cell-dependent tumour immunity." (PMID 38334623, 2024). "Mice with an R619W knock-in transgene (which corresponds to the human autoimmune-associated R620W alteration) exhibit better control of xenografted Hepa1-6.x1 tumor growth than wildtype mice, but less effectively than Ptpn22-deficient mice." (PMID 38022587, 2023). "It was suggested that increased IL-2 production by murine PTPN22 deficient T cells helped them overcome the suppressive effects of TGFβ in the tumor microenvironment." (PMID 33425916, 2020). "The enhanced antitumor responses of PTPN22-deficient T cells were associated with elevated reactivity to low-affinity tumor antigens and a decreased susceptibility to inhibition by tumor-derived TGF-β." (PMID 31335326, 2019). "We sought to determine the effect of PTPN22 deficiency on the capacity of CTLs to directly mediate target cell killing in response to strong and weak tumor-associated antigens (TAAs)." (PMID 31335326, 2019). "Given the critical dual role of TGFβ in limiting autoimmune and anti-tumor responses, we investigated the impact of PTPN22 deficiency on the responses of CD8+ T cells to this key inhibitory cytokine." (PMID 29116089, 2017). "Nonetheless, adoptive T cell transfer studies, using TCR transgenic T cells and ID8 ovarian carcinoma and EL4 lymphoma cells modified to express model antigens, demonstrated an enhanced capacity of PTPN22-deficient CD8+ T cells to clear established tumours in mice." (PMID 38334623, 2024). "It includes receptors that have been mechanistically linked to cancer progression such as the G protein coupled receptors CXCR3 and FZD6, linked to tumor cell growth, invasion and migration, and PTPN22, a protein tyrosine phosphatase associated with inhibition of antioncogenic immune response." (PMID 35875157, 2022). "Other recent work has also suggested that loss of PTPN22 might be beneficial for anti-tumor responses, since PTPN22–/– mice showed increased tumor rejections in combination with anti-PD-L1 immunotherapy." (PMID 33425916, 2020). "PTPN22 deficiency improves memory T cell–mediated tumor clearance." (PMID 31335326, 2019). "The results revealed that knockdown of PTPN22 led to a significant increase in infiltrating activated T cells, accompanied by a marked decrease in Treg cell infiltration within the tumor microenvironment." (PMID 41522360, 2026). "To investigate the role of PTPN22 in tumor growth both in vitro and in vivo, we conducted Cell Counting Kit-8 (CCK8) assays to evaluate cell proliferation in vitro and performed subcutaneous homograft assays in nude mice in vivo." (PMID 41522360, 2026). "To further investigate the potential role of PTPN22 in tumor cells, we systematically evaluated PTPN22 expression levels in tumor and normal tissues utilizing the Cancer Genome Atlas (TCGA) database." (PMID 41522360, 2026). "Immunohistochemistry results showed that PD-L1 expression was significantly downregulated in tumor tissues following PTPN22 knockdown." (PMID 41522360, 2026). "The results indicated that mice implanted with Renca cells in which PTPN22 was knocked down exhibited significantly slower tumor growth, as well as reduced final tumor size and weight, compared with the control group." (PMID 41522360, 2026). "Together, these data provide evidence that PTPN22 is a key negative regulator of anti-tumour immunity in both mice and humans." (PMID 38334623, 2024).
tumor (continued). "Given the function of protein tyrosine phosphatases (PTPs) like PTPN22 in tumorigenesis and disease, PTPN22’s involvement as a regulator of T cell activation, infection responses, autoimmunity, and anti-tumor immunity has emerged." (PMID 39451542, 2024). "The PTPN22 siRNA silencing results showed that the tumor invasion inhibitory activity of THY1 was lost in HONE1-THY1 and HK1-THY1 cells when PTPN22 was depleted." (PMID 37046850, 2023). "Similar to CD8+ T cells, tumor-infiltrating macrophages and NK cells were also increased within tumors of Ptpn22-/- mice." (PMID 38022587, 2023). "The importance of PTPN22 in the regulation of immune-mediated tumor control is supported by mouse and human data." (PMID 38022587, 2023). "PTPN22 is thought to regulate the observed anti-tumor immunity through its catalytic function based on the similar inhibition of Hepa1-6.x1 tumor growth observed with Ptpn22C227S inactive knock-in mice and PTPN22-deficient mice." (PMID 38022587, 2023). "High level mRNA expressions of PTPN7 and PTPN22 were significantly negatively correlated with tumor purity." (PMID 36226189, 2022). "Currently, research on PTPN22 is not only limited to autoimmune diseases, but more evidence indicates a considerable importance in tumor immunity." (PMID 35957898, 2022). "Implantation of syngeneic tumors in PTPN22-/- mice resulted in greater infiltration and activation of macrophages, NK cells and T cells, which in turn led to spontaneous tumor regression." (PMID 35957898, 2022). "A novel small molecule inhibitor of PTPN22, named L-1 has promoted anti-tumour immune responses dependent upon the activation of CD8+ T-cells and macrophage polarisation towards the anti-tumour M1 phenotype." (PMID 34960140, 2021). "Studies have shown that deletion of PTPN22 or PTPN2 in CD8 T cells improved tumor clearance in a number of mouse tumor models." (PMID 33425916, 2020). "A recent study has shown that tumor clearance was improved in PTPN22–/– mice when combined with anti-PD1 therapy, in support of this strategy." (PMID 33425916, 2020). "Using primary tumors expressing a weak TAA complicated analysis of memory cell formation, as we consistently found that ACT of Ptpn22–/– cells was substantially superior to control ACT in mediating tumor clearance." (PMID 31335326, 2019). "By limiting PTPN22 deficiency solely to T cells in the current study, cotransfer experiments showed that control and Ptpn22–/– memory phenotype OT-1 T cells had a similar capacity to form long-lived memory cells upon ACT to tumor-bearing recipients." (PMID 31335326, 2019). "The choice of a high-affinity TAA was to ensure that control and Ptpn22–/– CD8+ T cells were similarly capable of clearing the primary tumor." (PMID 31335326, 2019). "Cotransfer experiments were performed to compare the ability of control Ly5.1+ and Ptpn22–/– Ly5.2+ memory phenotype CD8+ T cells to persist in tumor-bearing hosts." (PMID 31335326, 2019). "Whereas hosts receiving either no ACT or control ACT succumbed to OVA-T4–bearing tumors within 12 days after challenge, mice (n = 7) receiving Ptpn22–/– memory phenotype cells remained entirely tumor free for at least 90 days following tumor cell injection." (PMID 31335326, 2019). "Remarkably, ACT of Ptpn22–/– memory phenotype T cells, 24 days prior to tumor challenge, completely prevented the development of EL4-OVA-T4 tumors in 100% of mice tested (13 of 13 mice in 2 experiments)." (PMID 31335326, 2019). "A quantitative methylation study of PTPN22 and its expression were conducted in 121 and 31 paired tumor and adjacent normal tissue (ANT), respectively." (PMID 27613842, 2016). "In the current study, the relative expression of the PTPN22 gene in tumor tissue was lower than that in ANT, although the difference was not significant." (PMID 27613842, 2016). "We found that the methylation level of PTPN22 was significantly elevated in tumor tissues (66.3%) relative to ANT (62.1%) (p=0.005)." (PMID 27613842, 2016).
tumor (continued). "In this study, we examined the methylation level of seven CpG sites in the selected region of PTPN22 (chr1:114,358,291-114,358,739 [GRCh37/hg19]) and observed that all seven sites exhibited hypermethylation in tumor tissue." (PMID 27613842, 2016). "Based on these observations, we hypothesized that PTPN22 may promote tumor progression by upregulating PD-L1 and fostering an immunosuppressive tumor microenvironment." (PMID 41522360, 2026). "Protein tyrosine phosphatase N22 (PTPN22), a protein tyrosine phosphatase that mediates proteins tyrosine dephosphorylation, is a negative regulator of T cell receptor signaling, but its role in tumor cells has been underappreciated." (PMID 41522360, 2026). "PTPN22 has the most significant multitarget intervention potential, while FAM175B and PROM2 are linked to tumor and inflammation pathways, and the specific interactions of LRRTM4 may guide precision treatment strategies." (PMID 40869128, 2025). "Furthermore, in vitro polarization of Ptpn22-/- OT-I T cells to a memory-like phenotype prior to ACT enabled prolonged retention of adoptively transferred T cells in vivo following tumor clearance." (PMID 39039893, 2024). "Thus, systemic administration of a PTPN22 selective inhibitor, L-1, reduced syngeneic tumor growth in Ptpn22+/+, but not Ptpn22-/-, mice and synergized with PD-1 blockade to mediate tumor clearance." (PMID 39039893, 2024). "Importantly, memory-phenotype PTPN22-deficient CD8+ T cells, polarized in vitro in the presence of IL-15, had the capacity to clear tumours and were retained in mice for months after tumours became undetectable." (PMID 38334623, 2024). "We analyzed the expression levels of PTPNs in the TCGA database and discovered that PTPN1, PTPN6, PTPN7, PTPN18, PTPN20, and PTPN22 were significantly upregulated in tumor samples, while PTPN4, PTPN5, PTPN10, PTPN11, PTPN13, PTPN14, and PTPN21 were downregulated in tumor samples." (PMID 36226189, 2022). "Since PTPN22 plays an important role in other signaling pathways, other mechanisms may further enhance tumor immunity." (PMID 35154122, 2022). "It is unclear whether inhibition of PTPN22 or SHP1 alone can significantly improve anti-tumour CD8+ T-cell responses however in combination with ICB in murine models has demonstrated improved efficacy compared to monotherapy." (PMID 34960140, 2021). "By this means, recently published data showed that downregulation of key proteins involved in T cells terminal differentiation and exhaustion such as NR4A, TOX/TOX2, TET2, Regnase1, or PTPN22 increased T cell-based treatment half-life and improve anti-tumor performance." (PMID 33287392, 2020). "In particular, responses to weak affinity tumor antigens were enhanced by knockout of PTPN22 which suggests that this strategy might be beneficial in promoting T cell responses to weaker TAAs." (PMID 33425916, 2020). "Control and Ptpn22–/– CTLs were equally effective in killing high-affinity ID8-N4 tumor cells." (PMID 31335326, 2019). "Importantly, upon transfer to naive recipient mice, very low numbers of long-lived Ptpn22–/– memory T cells provided enhanced protection from tumor challenge, as compared with control cells." (PMID 31335326, 2019). "Importantly, Ptpn22–/– effector CTL ACT enabled tumor clearance in response to both strong N4 and very weak V4 TAAs." (PMID 31335326, 2019). "The results showed that the ratio of control/Ptpn22–/– T cells remained approximately 1:1 for the duration of the experiment, indicating that PTPN22 deficiency does not impinge on T cell survival and longevity following tumor clearance." (PMID 31335326, 2019). "Flow cytometry analysis of host lymph nodes and spleens determined that a population of transferred central memory phenotype Ptpn22–/– CD8+CD44hiCD62L+ T cells could be detected at the experimental endpoint (day 90 after tumor challenge and day 104 after ACT)." (PMID 31335326, 2019).
tumor (continued). "Furthermore, long-lived Ptpn22–/– memory T cells retain their enhanced capacity to control tumor growth in vivo." (PMID 31335326, 2019). "Recent evidence suggesting that the PTPN22 might enhance the efficacy of anti-tumour T cell responses." (PMID 30139984, 2018). "In this regard, we showed that Ptpn22−/− T cells were superior to control cells in responding to both high- and low-affinity TSA and in mediating tumor rejection in vivo, suggesting that targeting PTPN22 may be a viable approach in T cell immunotherapies." (PMID 29116089, 2017). "The relative PTPN22 expression level was quantified in 43 paired tumor tissues and ANT." (PMID 27613842, 2016). "Additionally, the TCGA database showed that there was a significant difference in the methylation level of PTPN22 between tumor tissues and normal tissues." (PMID 27613842, 2016). "Similarly, we analyzed subcutaneous tumor tissues derived from PTPN22-knockdown cells." (PMID 41522360, 2026). "Given PTPN22’s role in regulating T cells and macrophages in tumor defense, we propose that PTPN22 inhibitors could emerge as a unique form of cancer immunotherapy with broad immunomodulatory effects, especially when combined with other immunotherapeutic strategies." (PMID 39451542, 2024). "Notably, L-1 treatment does not affect MC38 tumor growth in PTPN22-deficient mice, implying that its therapeutic benefits are mediated through host-expressed PTPN22." (PMID 38022587, 2023). "Furthermore, we sought to test the hypothesis that PTPN22 acts as a brake to limit the effectiveness of anti-tumor T cell responses." (PMID 29116089, 2017). "In particular, cotransfer experiments demonstrated that Ptpn22-/- CD8+ T cells initially proliferated more but assumed an exhausted PD-1+Slamf6- phenotype and died more rapidly than Ptpn22+/+ cells in ID8-OVA tumor-bearing mice." (PMID 39039893, 2024). "In our research, we confirmed that PTPN10 and PTPN22 expression in normal tissues is lower than that in PAAD tissues, and this expression is correlated with the tumor stage of patients with PAAD." (PMID 35154122, 2022). "As indicative of an enriched immune tumor microenvironment, we found CXCR3, ZAP70 and PTPN22; whereas others, such as TIMP1 and MAP2K3, had higher correlation with endothelial markers indicative of a tumor-induced angiogenic process." (PMID 35875157, 2022). "Moreover, PTPN22–/– Tregs were more suppressive and secreted more IL-10 than their wildtype counterparts which might promote a more suppressive tumor environment." (PMID 33425916, 2020). "Our previous experiments determined an enhanced capacity of Ptpn22–/– CD8+ T cells to produce IFN-γ and TNF in response to low-affinity peptide antigens and mediate tumor rejection upon ACT." (PMID 31335326, 2019). "Several previously known cancer-related genes, including PTPN22, BRIP1, and CEACAM6, were found as hubs in the tumor-related subnetworks." (PMID 30240439, 2018). "The deletion of PTPN22 did not improve the in vivo anti-tumour activity of murine HER2-specific CAR-T cells, reflecting a lack of effect of PTPN22-deficiency on very high-affinity T cell responses." (PMID 38334623, 2024). "CD8+ T-cells lacking PTPN22 demonstrate improved anti-tumour immunity and resistance to suppression mediated by TGF-β, via increased IL-2 expression." (PMID 34960140, 2021). "Nonetheless, we showed that ACT of Ptpn22–/– but not control memory phenotype T cells 14–24 days prior to tumor inoculation completely prevented growth of low-affinity EL4-OVA-T4 tumors." (PMID 31335326, 2019). "We previously reported that targeting expression of phosphotyrosine phosphatase, nonreceptor type 22 (PTPN22) in effector CD8+ T cells enhances the efficacy of ACT for tumor clearance in mice." (PMID 31335326, 2019). "Strikingly, low numbers (i.e., 104) of adoptively transferred Ptpn22–/–, but not control, memory T cells significantly reduced tumor burden in recipient mice." (PMID 31335326, 2019).
tumor (continued). "PTPN22 not only altered the composition of immune cells in the TME, promoting Tregs and macrophage infiltration, but further analysis also revealed a positive correlation between PTPN22 expression and Tumor Immune Dysfunction and Rejection (TIDE) immune dysfunction scores." (PMID 41522360, 2026). "In summary, PTPN22 does not directly regulate the growth or proliferation of tumor cells; rather, it promotes tumor progression by modulating PD-L1 expression, which in turn alters T cell infiltration within the tumor immune microenvironment." (PMID 41522360, 2026). "Conversely, enhanced T cell activation mediated by LIP in absence of PTPN22 could promote tumor immunity and be attractive for cancer therapies." (PMID 32047502, 2020). "The relative PTPN22 expression level was reduced in the tumor tissue compared with that in the corresponding ANT, but the difference was not statistically significant (ANT vs. tumor: 1 vs. 0.9, respectively; p=0.55)." (PMID 27613842, 2016). "Strikingly, Ptpn22–/–, but not control, memory phenotype T cell ACT could completely protect mice from low-affinity antigen-bearing tumors when transferred to hosts 2–4 weeks prior to tumor implantation." (PMID 31335326, 2019).